IL22 (interleukin 22)
Diseases named in the same sentence as IL22 in open-access papers (continued):
Sharing a sentence is not in itself a finding about the gene and the disease.
tuberculosis (continued). "Consistently, IL-22-producing T cells were visualized in situ in lung tuberculosis (TB) granulomas by confocal microscopy and immunohistochemistry, indicating that mature IL-22-producing T cells were present in TB granuloma." (PMID 20195465, 2010). "Our findings in the macaque TB model system raise the possibility to study cell-cell interaction and mutual regulation between Vγ2Vδ2 T cells and IL-22-producing T cells during M. tuberculosis infection." (PMID 20195465, 2010). "Six cytokines, i.e., IL-6, IP-10, IL-10, IL-22, IFN-γ, and GM-CSF, were significantly higher in plasma samples from patients with tuberculosis." (PMID 35759173, 2023). "Tuberculosis-driven IL-10-producing T cells might down-regulate human IL-22 and IL-17 producing Th17 cells in chronically-active TB." (PMID 20195465, 2010). "The presence of autoantibodies targeting cytokines has been noted in various infectious diseases: anti-interferon-α antibodies in severe SARS-CoV-2 infection; anti-interferon-γ antibodies in tuberculosis and anti-IL17A/IL-17 F/IL-22 in chronic mucocutaneous candidiasis." (PMID 40123018, 2025). "We also performed preliminary analysis of the cellular source of IL-10 and IL-22 and found both more frequently in CD14+ cells, consistent with increasing evidence that innate immune system activation is a component of the immunopathology of tuberculosis-IRIS." (PMID 23303806, 2013). "Our analysis of IL-10–related cytokines showed an increase in the transcript levels of IL-10 and IL-22 in tuberculosis-IRIS patients, compared with non-IRIS controls." (PMID 23303806, 2013). "Analysis of corresponding serum samples showed significantly higher concentrations of IL-10 and IL-22 in tuberculosis-IRIS patients, compared with non-IRIS patients." (PMID 23303806, 2013). "Moreover, IL-22 can promote the proliferation and recovery of pleural mesothelial cells (PMCs) and the closure of PMC layers, which facilitates protection of PMCs from tuberculosis-induced damage." (PMID 36839448, 2023). "Moreover, IL-23-dependent expansion of ILC3s in mice and the production of the cytokines IL-17 and IL-22 are critical inducers of lung CXCL13, promoting early mobilization of lung ILC3 and macrophages to initiate inflammation in an attempt to control tuberculosis." (PMID 37415827, 2023). "Thus, our results add to the knowledge that IL-22 is not crucial for protection as well also to the induction of a protective vaccine against tuberculosis." (PMID 27375607, 2016). "Similarly, IL-22 was found to be significantly upregulated at both 6 and 24 hours in cultures from tuberculosis-IRIS patients, compared with non-IRIS control patients (P = .004 and P = .0015, respectively)." (PMID 23303806, 2013). "It is not known either whether tuberculosis lesions in lung infection sites can preferentially drive expansion of T effectors cells actively producing IL-22 or IL-17." (PMID 20195465, 2010). "Interestingly, tuberculosis-driven T cells can actively produce IL-22 or IL-17 de novo without the requirement of in vitro antigen re-stimulation." (PMID 20195465, 2010). "Although human CD4 T cells have been shown to be important for protection against adult form of pulmonary tuberculosis, the role of IL-22-producing T cells in TB is not known." (PMID 20195465, 2010). "Similarly, serum IL-22 levels were significantly lower in tuberculosis (TB) patients with T2DM than in TB patients without T2DM." (PMID 31809521, 2019). "Therefore it is not surprised that the levels of IL-22 and IL-17 producing Th17 cells in active TB patients are lower than those in M. tuberculosis-exposed healthy controls." (PMID 20195465, 2010). "While IL-17 and IL-23 were investigated in mouse TB model, we have recently demonstrated that severe tuberculosis induces unbalanced up-regulation of immune gene networks and over-expression of IL-22 in nonhuman primates." (PMID 20195465, 2010).
tuberculosis (continued). "However, there are studies that support that IL-17 and IL-22 may not be necessary for the prevention of TB; for instance, wild type mice administered anti-IL-17A antibodies, as well as both IL-17RA and IL-22 KO mice, are not more susceptible to M. tuberculosis infection than the respective controls." (PMID 33530627, 2021).
candidiasis (25 papers, 2011 to 2025). Infection with the organism Candida. "Many studies showed that the secretion of IL-17, IL-22, and IL-23 can help the host resist Candida infections, and their absence can cause severe candidiasis." (PMID 35783379, 2022). "Indeed, the hallmark of candidiasis in autoimmune polyendocrinopathy-candidiasis-ectodermal dystrophy is the production of highly neutralizing autoantibodies against type I interferons and IL-22." (PMID 33921294, 2021). "IL-22 contributes to the clearance of oropharyngeal Candida infections and is essential for the clearance in individuals and mouse models with an impaired Th1 response, whereas, loss of IL-22 may be compensated in individuals with an intact Th1 response." (PMID 29967613, 2018). "Clearly, immune-effector responses may be reduced, as in the association of anti-IL22 with susceptibility to Candidiasis." (PMID 27426947, 2016). "Similarly, multiple patients with autoantibodies against TH-17 cytokines (comprising IL-17A, IL-17F, IL-22, IL-23) whose selective susceptibility to candidiasis strongly resembles inborn deficiencies with impaired production or response to IL-17 were described." (PMID 32419033, 2020). "Th17 cells are differentiated from CD4+ helper T cells, which secrete IL-17, IL-22, and other cytokines and play an essential role in the host's resistance to Candida infection." (PMID 35783379, 2022). "A previous study has shown that administration of IL-10 increased host susceptibility to candidiasis, while IL-17, IFN-γ, IL-12, and IL-22 played an important role in protecting against candida." (PMID 32460890, 2020). "Because indole-3-lactate can act as a ligand for AhR, we speculate that L. crispatus may regulate the IL-22-AhR response in the vagina, reducing the risk of vaginal candidiasis in the same way IAld does, and potentially activating the AhR response in newborns to prevent early-life candidiasis." (PMID 32843557, 2020). "Administration of the microbial metabolite indole-3-aldehyde, known to stimulate the production of IL-22 via the aryl hydrocarbon receptor (AhR), promoted IL-18 expression and protection against Candida infection." (PMID 31681274, 2019). "Indeed, the fact that IL-22 production is driven by commensals may explain how antibiotic therapy and iatrogenic immunosuppression are major predisposing factors in candidiasis and, more generally, how the bacterial-fungal population dynamics impact on vaginal homeostasis and inflammatory diseases." (PMID 23853597, 2013). "Autoantibodies against IL-22 and IL-17F seem to be correlated with chronic mucocutaneous candidiasis as previously reported, suggesting that Th17 cytokines are central in human epithelial immunity against candida infection." (PMID 38605470, 2025). "IL-22, synthesized by Th17 cells, contributes to host defense and protects against candidiasis." (PMID 40650232, 2025). "For this purpose, we evaluated the expression of genes downstream of AhR, such as cytochrome P450 family 1 subfamily A member 1 (Cyp1a1) and subfamily B member 1 (Cyp1b1) and Il22 in the lungs and colons of mice with aspergillosis and candidiasis, respectively." (PMID 38534388, 2024). "By contrast, antibody activities may be reliably reflected in discrete pathologies, as in the correlation of anti-IL22 with candidiasis." (PMID 27426947, 2016). "Mutations in IL17F, IL17R and DECTIN1 in patients with chronic mucocutaneous candidiasis, as well as neutralizing autoantibodies against IL-17 and IL-22 in patients with autoimmune polyendocrinopathy-candidiasis-ectodermal dystrophy, directly impair IL-17 and IL-22 immunity." (PMID 23853597, 2013). "Th17 cells secrete IL-17 and IL-22, which are cytokines with potent antifungal properties and the occurrence of autoantibodies against IL-17/IL-22 were reported to closely correlate to the presence of candida infection." (PMID 22876245, 2012). "Previous studies showed that IL-17, IL-22, and IL-23 could help resist Candida infections." (PMID 35783379, 2022).
candidiasis (continued). "In candidiasis, IL-22 is produced by innate (DCs and CD3− NKp46+ cells) and adaptive (TH17 and memory C. albicans-specific IL-22+CD4+ cells) immune cells, with IL-23 regulating IL-22 production by TH17 cells." (PMID 27303405, 2016). "Icld could promote the production of IL-22 via interaction with AHR, inducing the expression of IL-18 to inhibit Candida infection." (PMID 34361945, 2021). "In that line, the transcription of Interleukin-22 (IL-22) is AhR-dependently increased in type 3 innate lymphoid cells (ILC3), which balance the mucosal response to allow mixed microbial communities and homeostasis on one side but protect from candidiasis on the other." (PMID 34639632, 2021). "While Th1 response was initially thought to be the key mediator of immunity, more recent studies have supported critical role of IL-17- and IL-22-producing Th17, but not IFN-γ-producing Th1, response in protection against candidiasis." (PMID 27280548, 2016). "This is expected on the part of IL-22, which does not act on immune cells and is uninvolved in PMN recruitment to the oral mucosa in murine candidiasis." (PMID 25344377, 2014). "IL-22-induced STAT-3 phosphorylation was blocked in a similar fashion to patients with APECED, in only one anti-IL-22 autoantibody sera positive patient with SS, but who did not have candidiasis." (PMID 31892200, 2019).
atherosclerosis (23 papers, 2013 to 2025). A disease characterized by the build-up of fatty material and calcium deposition in the arterial wall resulting in partial or complete occlusion of the arterial lumen. "A study conducted to compare the effects of atherosclerosis on ApoE deficient mice vs. healthy mice has shown that the presence of Th22 and IL-22 was directly associated with the level of inflammation." (PMID 39944697, 2025). "By administering either recombinant IL-22 or neutralizing IL-22 antibody it was shown that IL-22 aggravates atherosclerosis, which was associated with increased macrophage and T cell infiltration in the blood vessels with a proportional increase in Th17 cells." (PMID 33692792, 2021). "Enforced IL-22 signaling by administration of recombinant protein rectified IL-23/IL-23R deficiency and ameliorated atherosclerosis." (PMID 33562334, 2021). "In addition, IL-22 within atherosclerosis was associated with the accumulation of cholesterol and attraction of M1 macrophages, resulting in the release of MMP-9 and various proinflammatory cytokines." (PMID 39944697, 2025). "Additionally, adalimumab treatment steadily reduced the levels of E-selectin, hs-CRP, and IL-22, suppressed systemic inflammation, and decreased the risk of atherosclerosis." (PMID 39399488, 2024). "However, genetic ablation of IL-23 or IL-23R in hematopoietic cells unexpectedly accelerates atherosclerosis development, particularly due to the loss of downstream IL-22 expression and IL-22-dependent intestinal homeostasis and host–microbiota détente." (PMID 33562334, 2021). "Thus, Th22 cell‐derived IL‐22 aggravates atherosclerosis development through a mechanism that is associated with IL‐6/STAT3 activation, DC‐induced Th17 cell proliferation and IL‐22–stimulated SMC dedifferentiation into a synthetic phenotype." (PMID 32022386, 2020). "As a primary source of IL-22, Th22 cells have been observed in various autoimmune illnesses and chronic inflammatory processes such as atherosclerosis." (PMID 39944697, 2025). "Recently, numerous studies showed that IL-22 is involved in the pathogenesis of atherosclerosis by regulating VSMC proliferation and migration, angiogenesis, inflammatory response, hypertension, and cholesterol metabolism." (PMID 37047399, 2023). "The exact role of IL-22 in atherosclerosis is still controversial, although most studies point to the pro-atherogenic function of IL-22." (PMID 37047399, 2023). "Human studies have also observed a correlation between circulating IL-22 levels and atherosclerosis." (PMID 35600479, 2022). "IL-22 expression was shown to be increased in high-fat diet-fed ApoE-/- mice and to promote the development of atherosclerosis, while IL-22 deletion exerted an antiatherosclerotic effect." (PMID 35340206, 2022). "On the one hand, IL-22 worsens atherosclerosis by promoting inflammation, dysregulating macrophage cholesterol metabolism leading to more foam cell formation and promoting VSMCs proliferation and fibrous cap thickening." (PMID 35600479, 2022). "The authors concluded that IL-22 secretion by Th22 aggravates atherosclerosis by promoting T cells (Th17), DCs and macrophage infiltration in the plaque and by inducing the dedifferentiation of contractile SMCs into synthetic SMCs." (PMID 35600479, 2022). "In the future, more data are required to reveal the exact role of IL-22 in these effector cells during the development of atherosclerosis." (PMID 34388961, 2021). "Although Th1 and Th17 cells play a role in the development of atherosclerosis, Th22 cell-derived IL-22 is more important in atherosclerosis." (PMID 34388961, 2021). "The precise role of IL-22 in atherosclerosis is still controversial, although most studies suggest a proatherogenic function of IL-22." (PMID 34388961, 2021). "The role of IL-22 has been investigated using a mouse model in which atherosclerosis is induced by feeding ApoE−/− mice a so called western diet." (PMID 33692792, 2021).
atherosclerosis (continued). "In this review, we focus on the latest advance regarding the regulation and signaling pathways of IL-22 and highlight its impacts on atherosclerosis." (PMID 34388961, 2021). "Similar to IL-22, IL-1β is expressed in a variety of cell types related to the development of atherosclerosis including endothelial cells, macrophages, and VSMCs." (PMID 34388961, 2021). "The answers to these sorts of questions will undoubtedly provide unique insights into the roles of IL‐22 in atherosclerosis and make IL‐22 an attractive therapeutic target for therapy aiming at the reduction of atherogenesis." (PMID 34388961, 2021). "Third, as an important proinflammatory cytokine, does IL‐22 play a role in pyroptosis (a pivotal driver of atherosclerosis)?" (PMID 34388961, 2021). "Some clinical data have demonstrated that IL-22 levels are strikingly elevated in patients with atherosclerosis cardiovascular disease, which positively correlated with the proinflammatory cytokine levels (CXCL-11, CXCL-10, and CXCL-9) in carotid plaques." (PMID 34388961, 2021). "IL-22 plays a critical role in the development of atherosclerosis through its involvement in the modulation of angiogenesis, inflammatory response, hypertension, VSMC proliferation and migration, and cholesterol metabolism." (PMID 34388961, 2021). "Recently, numerous studies suggest that IL-22 is involved in the pathogenesis of atherosclerosis by regulation of VSMC proliferation and migration, angiogenesis, inflammatory response, hypertension, and cholesterol metabolism." (PMID 34388961, 2021). "As a unique and pleiotropic cytokine, IL-22 promotes the development of atherosclerosis through multiple mechanisms." (PMID 34388961, 2021). "They found that ablation of IL-22 exacerbates atherosclerosis and IL-22 administration suppresses the atherosclerosis development." (PMID 31501353, 2019). "Pg-immunized mice with extensive atherosclerosis had lower IL-5, IL-10 and IL-22 levels than those with less atherosclerosis." (PMID 29329335, 2018). "In the case of atherosclerosis, IL-22 −/−Apoe −/− mice exhibited reduced plaque size and decreased plaque collagen level, which are important in the maintenance of plaque stability." (PMID 27829708, 2016). "Taken together, the results indicate that Th22 response is pivotal in the development of atherosclerosis and the onset of acute coronary syndrome by virtue of the secretion of IL-22." (PMID 24453425, 2013). "Moreover, in another study of atherosclerosis, IL-22R1 and IL-22 are expressed in atherosclerotic plaques of mice, and their expression levels are significantly increased in mice with apoE knockout." (PMID 37047399, 2023). "The role of IL-22 in atherosclerosis is pleiotropic through multiple mechanisms." (PMID 37600028, 2023). "Since atherosclerosis is also an inflammatory disease, interfering with IL-22 or IL-22 receptor may also represent a promising therapeutic target for CVD, although more elaborate research is needed to pinpoint the exact mechanisms of action." (PMID 35600479, 2022). "Overall, increasing studies support the view that targeting IL-22 may be a promising therapeutic strategy for atherosclerosis." (PMID 34388961, 2021).